PECR (peroxisomal trans-2-enoyl-CoA reductase)
Description:
Participates in chain elongation of fatty acids. Catalyzes the reduction of trans-2-enoyl-CoAs of varying chain lengths from 6:1 to 16:1, having maximum activity with 10:1 CoA. Has no 2,4-dienoyl-CoA reductase activity.
Synonyms: TERP; SDR29C1; HSA250303; DCRRP; HPDHASE; PVIARL
Tractability: Small molecule: a structure with a bound ligand is known; it has a high-quality binding pocket. PROTAC: ubiquitination databases record sites on it; its protein half-life has been measured.
Gene: Protein-coding gene on chromosome 2 (215,996,329 to 216,082,955, reverse strand). Ensembl gene ENSG00000115425.
Subcellular location: Peroxisome
Subcellular location (Human Protein Atlas): Peroxisomes
Pathways (Reactome):
Metabolism: Alpha-oxidation of phytanate
Protein localization: Peroxisomal protein import
Gene Ontology:
Molecular function: 2,4-dienoyl-CoA reductase (NADPH) activity; signaling receptor binding; trans-2-enoyl-CoA reductase (NADPH) activity
Biological process: phytol metabolic process; fatty acid biosynthetic process
Cellular component: peroxisome; cytosol; peroxisomal membrane; cytoplasm; mitochondrion
Genetic constraint (gnomAD): Loss-of-function variants: 13 observed, 11.49 expected, observed/expected ratio (o/e) 1.13, 90% interval 0.73 to 1.74. The upper end of that interval is the gene's LOEUF score, 1.74, which puts it in group 6 of 6, group 1 being the genes least tolerant of losing a copy. Missense variants: 133 observed, 129.6 expected, observed/expected ratio (o/e) 1.03, 90% interval 0.89 to 1.18. Synonymous variants: 48 observed, 54.66 expected, observed/expected ratio (o/e) 0.88, 90% interval 0.7 to 1.12.
Homologues: Orthologues: chimpanzee PECR (99% identical), macaque PECR (85% identical), rabbit PECR (78% identical), dog PECR (75% identical), guinea pig PECR (75% identical), pig PECR (74% identical), mouse Pecr (73% identical), rat Pecr (62% identical), zebrafish pecr (58% identical).
Diseases named in the same sentence as PECR in open-access papers:
PECR is named in the same sentence as 10 diseases in open-access papers, as found by Europe PMC text mining. Sharing a sentence is not in itself a finding about the gene and the disease. The quoted sentences say what the papers report.
COVID-19 (1 paper, 2024). A disease caused by infection with severe acute respiratory syndrome coronavirus 2. "Therefore, ACOX2 and PECR may regulate the expression of SCD during the development of COVID-19, thus affecting the occurrence and development of AMD." (PMID 38625951, 2024). "Therefore, we explored the common pathogenesis of AMD and SARS-CoV-2, and found that COVID-19 and AMD have five common differences in FAMRG, namely FASD1, HMGCS1, ACOX2, ACAT2 and PECR." (PMID 38625951, 2024). "At the same time, we found that ACOX2 and PECR, as genes for fatty acid metabolism, may regulate the expression of SCD during the occurrence and development of COVID-19, thus affecting the occurrence and development of AMD." (PMID 38625951, 2024).
dyslipidaemia (1 paper, 2025). "Our study confirmed key proteins (PCSK9, ANGPTL3, LPA), identified potential novel targets (GSTA1, GSTA3, EPPK1, PECR, and PLA2G15), and strengthened evidence for CELSR2 and GAS6 in dyslipidaemia." (PMID 40689090, 2025).
psoriasis (1 paper, 2024). An autoimmune condition characterized by red, well-delineated plaques with silvery scales that are usually on the extensor surfaces and scalp. "The upregulation of genes such as ELOVL3 and PECR in non‐lesional skin and ELOVL3 and FADS2 in plaque skin may improve lipid barrier function, suggesting that bevacizumab could potentially alleviate epidermal barrier dysfunction and limit disease progression in psoriasis." (PMID 39624732, 2024).
Salmonella Infections (1 paper, 2021). Infections with bacteria of the genus SALMONELLA. "We also identified some new host proteins that have never been reported in Salmonella infection previously, such as indolethylamine N-methyltransferase (INMT) and peroxisomal trans-2-enoyl-CoA reductase (PECR)." (PMID 34461813, 2021).
sarcopenia (1 paper, 2026). Progressive decline in muscle mass due to aging which results in decreased functional capacity of muscles. "The FABP3 (P < 0.001), PECR (P < 0.01), and OPN3 (P < 0.001) mRNA expression markedly increased in sarcopenia versus control groups." (PMID 41460756, 2026). "The qPCR results demonstrated that FABP3 (P < 0.001), PECR (P < 0.01), and OPN3 (P < 0.001) expression markedly increased in D‐gal‐induced sarcopenia compared with control groups, whereas PCTP (P < 0.001), SREBF2 (P < 0.001), and PPARGC1A (P < 0.05) levels dramatically decreased." (PMID 41460756, 2026).
cancer (1 paper, 2020). A tumor composed of atypical neoplastic, often pleomorphic cells that invade other tissues. "While little is known about the functional involvement of BRWD3 and PECR in human cancers, an enrichment of FOS as part of a heterodimer with JUN has previously been linked to anchorage-independent cell growth in our HPV-transformed cell lines as well as HeLa." (PMID 32188026, 2020).
PECR also shares sentences with these, for which no sentence is quoted: alcoholism (1 paper); Alzheimer disease (1); ovarian carcinoma (1); tumor (1).